PCAT1 (prostate cancer associated transcript 1)
Diseases named in the same sentence as PCAT1 in open-access papers (continued):
Sharing a sentence is not in itself a finding about the gene and the disease.
prostate carcinoma (continued). "In addition, PCAT1 contributes to the progression of prostate cancer by activating AKT and NF-κB signaling." (PMID 35075115, 2022). "Within the down-regulated gene set, we note a number of genes that have previously been associated with increased proliferation in prostate cancer; these include kallikrein 2 (KLK2), long non-coding RNA prostate cancer associated transcript 1 (PCAT1), Vav guanine nucleotide exchange factor 3 (VAV3)." (PMID 33596994, 2021). "Within lncRNA PCAT1, a significantly hypermethylated m6A peak enriched in exon 2 was shown in tumor tissues and has been reported to suppress castration-resistant prostate cancer progression by activating AKT and NF-κB signaling." (PMID 34868913, 2021). "In the LNCaP prostate cancer cell line, PCAT1 knockdown led to an increased BRCA2 protein expression, while PCAT1 overexpression decreased BRCA2 protein level and impaired repair of double-strand brakes, thus sensitizing cells to PARP1 inhibitors and radiation." (PMID 33918762, 2021). "In addition, PCAT1 is a long non-coding RNA, which is known to be upregulated in prostate cancer and negatively regulates BRCA2 expression while positively affecting MYC expression." (PMID 31748536, 2019). "PCAT-1 regulates c-Myc expression in prostate cancer cell lines." (PMID 30987615, 2019). "PCAT-1 was initially identified as an oncogene in prostate cancer." (PMID 30987615, 2019). "However, the clinical relevance of PCAT1 expression in prostate cancer progression and castration-resistance remains largely unexplored." (PMID 30773595, 2019). "In addition, PCAT-1–mediated proliferation in prostate cancer cells has been shown to be exerted through cMyc protein stabilization." (PMID 28989584, 2017). "Besides the involvement of PCAT1 in prostate cancer, PCAT1 was also found to be overexpressed in CRC tumors." (PMID 28930145, 2017). "For instance, inhibiting PCAT-1 expression in CRC suppresses MYC mRNA expression, which may be explained by findings in prostate cancer where PCAT-1 regulates the binding between miR-34A and the 3 ‘untranslated region (UTR) of MYC mRNA, thus reducing its translation." (PMID 39075086, 2024). "Furthermore, prostate cancer patients could be stratified into distinct groups expressing either high levels of PRC 2 components or of the proliferation-promoting lncRNA PCAT1." (PMID 33329688, 2020). "Besides PCAT1, several other lncRNAs have prognostic potential in prostate cancer." (PMID 33329688, 2020). "Furthermore, PCAT-1 targeted c-Myc to display its functions in prostate cancer." (PMID 31777580, 2019). "PCAT-1 promotes proliferation through the oncoprotein Myc, while VAV3 regulates AR activity to stimulate growth in prostate cancer." (PMID 33596994, 2021). "Deeper examination found the common thread linking down-regulated genes was involvement in proliferation, including several known to increase prostate cancer proliferation (KLK2, PCAT1 and VAV3)." (PMID 33596994, 2021). "Together, these chromatin-conformation data suggest that the rs72725854-harboring enhancer forms a spatial network with PCAT1, PRNCR1, PVT1, and MYC genes in 3D nuclear space in prostate cancer cells." (PMID 32680982, 2020). "We used PCAT1, EZH2, and SChLAP1 as control genes, all of which have elevated expression in prostate cancer metastases." (PMID 24727738, 2014). "In prostate cancer, several lncRNAs, including PCA3 and PCAT-1, have been shown to be upregulated in patients with cancer." (PMID 24727738, 2014). "For example, we found human lincRNAs NAG7, MEG3, PCAT1, CASC2 and LINC00032, which were involved in nasopharyngeal carcinoma, glioma and bladder cancer, prostate cancer, endometrial cancer and melanoma." (PMID 25075616, 2014). "Long non-coding RNAs, including PCGEM, PCAT-1, MALAT, and the prostate cancer gene 3 (PCA3), have recently been discovered to be deregulated in PC, describing the PCA3 gene’s extreme over expression in prostatic cancers." (PMID 38723038, 2024).
prostate carcinoma (continued). "In a novel development, the PCA3 prostate cancer gene, PCAT-1, MALAT-1 PCGEM, and several other long non-coding RNAs were investigated for potential deregulation in PC." (PMID 38723038, 2024). "For instance, PCAT1, PVT1, and PCAT19 in prostate cancer, CUPID1 and CUPID2 in breast cancer, PTCSC2 and PTCSC3 in thyroid cancer, LINC00673 in pancreatic cancer, lncPSCA in gastric cancer, as well as LCETRL3 and LCETRL4 in non-small cell lung cancer, are implicated in malignant development." (PMID 37072811, 2023). "PCAT1 interacts with AR and LSD1 to promote prostate cancer progression." (PMID 35592755, 2022). "A previous study has shown that PCAT1 could also inhibit BRCA2 expression and modulate the stabilization of MYC as a prostate cancer promoter." (PMID 35592755, 2022). "Subsequently, the PCAT1 transcript interacts with the LSD1 and AR proteins facilitating their recruitment to enhancer regulatory elements of GNMT and DHCR24 that are androgen-late response genes that correlate with prostate cancer progression." (PMID 34449663, 2021). "Besides, PCAT1 cooperates with AR and LSD1 and is necessary for their gathering at the enhancers of two androgen late-response genes involved in prostate cancer tumorigenesis." (PMID 28989584, 2017). "PCAT-1 maps in the 8q24 locus, which is frequently amplified in prostate cancer; however, it was shown that PCAT-1 upregulation is not dependent on genomic amplification." (PMID 29165379, 2017). "PCAT-1 knockdown increases cell proliferation, suggesting that PCAT-1 might contribute to prostate cancer progression." (PMID 28124977, 2017). "Moreover, down-regulation of PCAT-1 by interference RNA was enough to reduce cell proliferation in vitro, pointing to PCAT-1 as a potential therapeutic target of prostate cancer." (PMID 27148353, 2016). "Several lncRNAs have been used as diagnostic and prognostic markers, including the following: MALAT-1 for liver, lung, breast, and prostate cancer; HOTAIR for breast, brain, and colon cancer; OOC1 for colon cancer; and PCA3, PCAT-1, and SChLAP1 for prostate cancer." (PMID 26160837, 2015). "Moreover, PCAT1 was identified as an androgen late-response gene and interacted with AR and lysine-specific demethylase 1 (LSD1) upon prolonged androgen treatment to promote prostate cancer growth." (PMID 34946977, 2021).
colorectal cancer (22 papers, 2017 to 2025). A primary or metastatic malignant neoplasm that affects the colon or rectum. "Several other studies have discussed the association between PCAT-1 and a variety of types of human malignancies, such as hepatocellular carcinoma, gastric carcinoma, colorectal carcinoma, esophageal carcinoma, cervical carcinoma and osteosarcoma." (PMID 40468332, 2025). "The lncRNA prostate-associated transcript 1 (PCAT1) is a well-known oncogene that was found to be upregulated in colorectal cancer tissues and exosomes derived from colorectal patients." (PMID 36551531, 2022). "To further clarify the influence of PCAT1 on tumor formation and colorectal cancer metastasis, we constructed a nude mouse model of subcutaneous implantation tumors of colon cancer and liver metastasis of colon cancer." (PMID 36093435, 2022). "This study explored the colorectal cancer exosome lncRNA prostate cancer associated transcript 1– (PCAT1) mediated circulating tumors and the mechanism of cell colorectal cancer liver metastasis." (PMID 36093435, 2022). "This study is based on the influence of colorectal cancer exosome lncRNA PCAT1 on the biological behavior of circulating tumor cells." (PMID 36093435, 2022). "Although abnormal expression of PCAT1 has also been found in colorectal cancer, its role in colorectal cancer remains to be further studied." (PMID 36093435, 2022). "In a mouse model of colorectal cancer liver metastasis, knocking down PCAT1 significantly reduced the nodules formed by liver metastasis in mice." (PMID 36093435, 2022). "PCAT-1 has been suggested to be biomarker for poor prognosis of colorectal cancers and we found the levels of this lncRNA only slightly elevated." (PMID 34307387, 2021). "The study suggested that lncRNA PCAT1 might co-ordinate ZNF217 to enhance colorectal cancer progression through the regulation of an EMT axis involving two metastasis-associated 1 family members (MTA2/MTA3) and Snai1/E-cadherin." (PMID 36551531, 2022). "To further explore the specific molecular mechanism of colorectal cancer exosomal PCAT1 in the development of colorectal cancer, we cocultured exosomes with T84 cells and then transfected the cells with sh-PCAT1 or cotransfected them with sh-PCAT1 + miR-329-3p inhibitor or sh-PCAT1 + oe-Netrin-1." (PMID 36093435, 2022). "In this study, we extracted exosomes from NCM460 cells and the primary colorectal cancer cell lines HCT116 and SW480 and found that the content of exosomes was different and the expression of the long noncoding RNA PCAT1 was abnormally high in colorectal cancer cell lines." (PMID 36093435, 2022). "Similarly, another study reported PCAT-1 modulated c-Myc and promoted colorectal cancer cells metastasis and multi-drug resistance." (PMID 31777580, 2019). "These include but are not restricted to lncRNAs like HOTAIR, Pvt1, RoR, prostate cancer–associated transcript 1 (PCAT1), ANRIL, H19, nuclear enriched abundant transcript 1 (NEAT1), UCA1, lung adenocarcinoma transcript 1 (LUADT1), colorectal cancer–associated lncRNA (CCAL), and many more." (PMID 30296263, 2018). "In addition, PCAT-1 has been shown to be significantly over-expressed in about two-thirds of colorectal cancer tissues compared with the matched normal tissues." (PMID 28989584, 2017). "Therefore, exosomes were cultured with T84 cells and HUVECs, and EMT-related protein expression and fibroactin formation were detected to determine whether PCAT1 promotes colorectal cancer by affecting the EMT process and fibroactin formation." (PMID 36093435, 2022). "Moreover, prostate cancer-associated transcript 1 (PCAT-1), a newly identified lncRNA, is dysregulated and functions as an oncogene in cancer; specifically, high expression of PCAT-1 is correlated with colorectal cancer (CRC) progression." (PMID 35071016, 2021). "CDKN2B-AS1 and TMEM220-AS1 were significantly downregulated in colon cancer, whereas LINC02257, PCAT1, and CASC8 were significantly upregulated in colorectal cancer." (PMID 41144378, 2025).
colorectal cancer (continued). "On this basis, we further confirmed that PCAT1 can affect the Netrin-1-CD146 complex by regulating miR-329-3p, thus affecting the EMT process and liver metastasis process of colorectal cancer." (PMID 36093435, 2022). "PCAT1 and CCAT1 have been identified as prognostic markers in prostate and colorectal cancers acting as transcriptional regulators of the genes BRCA2 and MYC respectively." (PMID 28945760, 2017). "The study finally found that the lncRNA PCAT1 derived from colorectal cancer acts as the ceRNA of miR-329-3p to regulate Netrin-1 in CTCs to promote the EMT process and affect the liver metastasis of colorectal cancer." (PMID 36093435, 2022).
bladder cancer (21 papers, 2014 to 2025). "Transcript levels of ANRIL and PCAT-1 in urinary exosomes are potential diagnostic biomarkers in bladder cancer." (PMID 32231490, 2020). "Another study showed that exosome-lncRNAs ANRIL and PCAT-1 in urine could serve as potential diagnostic biomarkers for bladder cancer, with AUCs of 0.7229 (sensitivity of 46.67% and specificity of 87.5%) and 0.7292 (sensitivity of 43.33% and specificity of 87.5%), respectively." (PMID 37592177, 2023). "The overexpression of PCAT1 enhances the proliferation and metastasis of non-small-cell lung cancer and bladder cancer." (PMID 40428349, 2025). "Specific lncRNAs, such as PCAT-1, UBC-1, and SNHG16, have been found to be significantly increased in the serum of bladder cancer patients, suggesting their potential as diagnostic markers." (PMID 40395335, 2025). "Urinary EVs lncRNA PCAT‐1 and MALAT1 overexpression in bladder cancer were linked to a poor recurrence‐free survival rate and facilitated recurrence prediction." (PMID 39611045, 2024). "In bladder cancer, TFAP2C transcriptionally increases prostate cancer associated transcript 1 (PCAT1) expression, which physically interacts with c-Myc to transcriptionally activate SLC7A11 expression." (PMID 37291585, 2023). "Silencing of PCAT-1 reportedly increases the cell proliferation arrest and apoptosis in human bladder cancers." (PMID 31319040, 2020). "Additionally, a novel biomarker of bladder cancer has been found is exosome, numerous studies investigating the association between exosomes and bladder cancer have identified the presence of exosome MALAT1, PCAT-1, and PTENP17." (PMID 38594513, 2024). "Additionally, higher urinary exosomal HOTAIR, MALAT1, PCAT-1, higher plasma exosomal H19, and higher serum exosomal UBC1 in NMIBC were associated with poorer prognosis of bladder cancer patients." (PMID 32517366, 2020). "Importantly, PCAT1 is reported to be upregulated in the serum of multiple myeloma patients and the urine of bladder cancer patients and is closely related to clinical diagnosis or prognosis." (PMID 31273188, 2019). "The combination of three lncRNAs (MALAT1, PCAT-1, and SPRY4-IT1) had an area under the ROC curve (AUC) of 0.854 for bladder cancer diagnosis, which was significantly higher than that for urine cytology (0.619)." (PMID 37592177, 2023). "Zhan and et.al developed a urinary exosome-derived lncRNA panel (MALAT1, PCAT-1 and SPRY4-IT1) for diagnosis and recurrence prediction of bladder cancer in a cohort consist of 368 urine samples." (PMID 34861847, 2021). "Screening for novel urinary EV lncRNA candidates for bladder cancer diagnosis identified MALAT1, PCAT-1, and SPRY4-IT1 differential expression to be of high diagnostic value in a training set consisting of 208 urine samples, which was subsequently confirmed in a validation set (160 urine samples)." (PMID 39585046, 2024). "Exosomal MALAT1, PCAT-1 and PTENP1 have been found in many studies focused on the link between exosomes and bladder cancer, indicating these three molecules participate in the progression of bladder cancer in depth." (PMID 37805491, 2023). "For example, higher urinary exosomal LNMAT2, higher urinary and serum exosomal circPRMT5, higher serum exosomal UCA1, the PCAT-1, UBC1, SNHG16 panel, higher plasma exosomal H19 and lower plasma exosomal PTENP1 were more frequently observed in bladder cancer patients than in healthy controls." (PMID 32517366, 2020).
gastric cancer (17 papers, 2018 to 2025). A primary or metastatic malignant neoplasm involving the stomach. "Furthermore, the long non-coding RNA (lncRNA) prostate cancer-associated transcript 1 (PCAT-1) was found to be upregulated in cisplatin resistant gastric cancer cells." (PMID 39703687, 2024). "Many oncogenic lncRNAs, including nuclear paraspeckle assembly transcript 1 (NEAT1), MALAT1, UCA1, and prostate cancer-associated transcript 1 (PCAT-1), as well as some tumor suppressor lncRNAs, have been shown to play a role in gastric cancer chemoresistance." (PMID 38294554, 2024). "In gastric cancer cells, PCAT-1 induces the resistance of cancer cells into cisplatin therapy by stimulation of ZEB1 through miR-128 inhibition, leading to the enhanced progression and malignancy of gastric cancer cells." (PMID 32664703, 2020). "More importantly, the knockdown of either HOXD-AS1 or PCAT-1 enhances the sensitivity of DDP-resistant gastric cancer cells to DDP." (PMID 32460771, 2020). "Other studies also demonstrated the oncogenic role of PCAT1 in gastric cancer, hepatocellular carcinoma, non-small cell lung cancer and bladder cancer." (PMID 30773595, 2019). "These include the action of PCAT-1 (Prostate Cancer-Associated Transcript 1), which epigenetically silenced PTEN (Phosphatase and Tensin Homolog) via recruiting EZH2 in BGC823/CDDP and SGC7901/CDDP cisplatin-resistant gastric cancer cell lines." (PMID 36230683, 2022). "For example, lncRNA PCAT-1, which is significantly expressed in tissues and cells of gastric cancer resistant to DDP, increases DDP resistance in gastric cancer cells by engaging EZH2 to epigenetically repress PTEN expression and controlling the miR-128/ZEB1 axis." (PMID 38162289, 2023). "LncRNA PCAT-1 is up-regulated and could play an oncogenic role in multiple cancers, such as prostate cancer, ESCC, gastric cancer, ovarian cancer." (PMID 35645836, 2022). "For instance, lncRNA PCAT-1, a highly expressed lncRNA in DDP-resistant gastric cancer tissues and cells, promotes DDP resistance of gastric cancer cells via epigenetically suppressing PTEN expression by recruiting EZH2, as well as regulating the miR-128/ZEB1 axis." (PMID 32192494, 2020). "PCAT-1 confers DDP resistance in gastric cancer (GC) cells through the miR-128/ZEB1 axis, providing a promising therapeutic strategy for GC." (PMID 33980216, 2021).